CD47 (CD47 molecule)
Diseases named in the same sentence as CD47 in open-access papers (continued):
Sharing a sentence is not in itself a finding about the gene and the disease.
tumor (continued). "In tumor cells, CD47 is frequently overexpressed and binds to the inhibitory receptor SIRPα, primarily expressed on myeloid cells, thus facilitating innate immune escape." (PMID 41514569, 2025). "Studies have demonstrated that dual inhibition of CD47 and PD-L1 induced complete tumor progression in murine models." (PMID 40070841, 2025). "These viruses produce locally generated nanobodies that block CD47/SIRPα interactions on tumor cells while sparing red blood cells, simultaneously reprogramming TAMs to phagocytic states and enhancing immune cell infiltration." (PMID 41355895, 2025). "Activation of the CD47-SIRPα signaling cascade allows tumor cells to evade immune surveillance and suppress the phagocytic capacity of TAMs." (PMID 39941714, 2025). "Beyond its role in suppressing phagocytosis, the CD47-SIRPα interaction also regulates the activation of innate immune cells, broadly dampening the anti-tumor immune response." (PMID 40529368, 2025). "The interaction between CD47 on tumor cells and signal regulatory protein alpha (SIRPα) on phagocytes delivers an antiphagocytic signal." (PMID 41488615, 2025). "CD47, overexpressed on tumor cells, interacts with SIRPα on macrophages, delivering a “do not eat me” signal that inhibits phagocytosis." (PMID 40806636, 2025). "Targeting CD47 with mAbs has been shown to block the CD47–SIRPα signaling axis and thus, leads to enhanced phagocytosis of tumor cells." (PMID 40402266, 2025). "Subsequently, the synergistic anti-tumor effects of CAR-M and oAd-CD47 and their underlying mechanisms were explored." (PMID 40814015, 2025). "A spatial transcriptomic study in liver cancer revealed that PROM1+ and CD47+ CSCs niches are associated with TME remodeling and tumor metastasis." (PMID 41316282, 2025). "Clinically, CD47 targeting is constrained by on-target, off-tumor toxicity since CD47 is expressed on normal cells, posing safety risks." (PMID 41511303, 2025). "CD47-targeted CAR-Ms combine tumor phagocytosis with secretion of IL-12 and GM-CSF, leading to TAM repolarization and promoting CD8+ T cell infiltration." (PMID 41341574, 2025). "Chimeric antigen receptor macrophages (CAR-Ms) dual-targeting HER2/CD47 phagocytose antigen-specific tumor cells." (PMID 40607254, 2025). "The statistical results of bioluminescence signals showed that both CAR-Ms group and oAd-CD47 group had significant tumor reduction to varying degrees after the initial administration, but the tumor size in increased over time." (PMID 40814015, 2025). "In conclusion, our findings suggest that the combination of CAR-Ms and oAd-CD47 exhibits potentially synergistic anti-tumor activity in the tested preclinical models." (PMID 40814015, 2025). "Implanted tumor model analysis showed that overexpressed CD47 markedly promoted tumor growth and increased tumor weight, but CD47/K16R mutant reversed this event." (PMID 39665172, 2025). "In line with this, we showed that IgA mAbs against EpCAM can activate neutrophils to lyse various PDAC cell lines and tumor cells, which can be augmented by addition of CD47 blockade." (PMID 40358156, 2025). "Here we found that TRAF2 induced CD47 ubiquitination, leading to inhibition of CD47 autophagic degradation, which in turn facilitated tumor immune escape." (PMID 39665172, 2025). "The immune checkpoint axis formed by SIRPα, expressed on phagocytes including TAMs, and CD47 on tumor cells inhibits intracellular signaling cascades, thereby negatively regulating phagocytic activity and enabling tumor cells to evade immune elimination." (PMID 40563367, 2025). "Several studies have reported that THBS1 interaction with CD47 on NK cells and cytotoxic T cells inhibits their activation and limits granzyme B production that mediates antigen-dependent lysis of tumor cells." (PMID 41019041, 2025).
tumor (continued). "The “don’t eat me” signal is released by CD47 in conjunction with its receptor, SIRPα, on macrophages, which weakens macrophage phagocytosis, thereby facilitating tumor cell escape from immune surveillance and clearance." (PMID 40051791, 2025). "Photosensitizers engineered for spatiotemporal modulation of cluster of differentiation 47 (CD47) in hypoxic tumor microenvironments (TMEs) disrupt immunosuppressive circuits." (PMID 41298247, 2025). "Emerging clinical trials targeting the CD47-SIRPα axis have shown enhanced macrophage-mediated phagocytosis and tumor clearance, particularly when combined with checkpoint inhibitors or chemotherapy." (PMID 40396172, 2025). "The dual blockade of galectin-3 (Gal-3) and CD47 synergistically suppressed tumor growth, increased phagocytosis, repolarized macrophages, and increased T-cell immune responses." (PMID 40732268, 2025). "The expression of a tumor immune tolerance induction marker, CD-47, significantly increased in H841 shANXA1 cells in comparison with H841 shCTRL cells." (PMID 40361334, 2025). "Enhanced phagocytosis: A key strategy to reinvigorate anti-tumor immunity is the therapeutic blockade of the CD47-SIRPα checkpoint." (PMID 41164198, 2025). "We rationally designed an anti-PD-L1 × CD47 aptamer-siRNA chimera to simultaneously block two distinct but complementary immune evasion pathways in tumor-infiltrating Treg cells." (PMID 41402667, 2025). "The dual-blocking mechanism effectively neutralized the “don’t eat me” signal by simultaneously targeting SIRPα on macrophages and CD47 on tumor cells, thereby circumventing tumor immune evasion." (PMID 40948940, 2025). "This downregulation of CD47 expression serves as a pivotal mechanism that significantly amplifies the phagocytic activity of macrophages against tumor cells, thereby reinforcing the immune system’s innate capacity to combat malignancy." (PMID 40070841, 2025). "Targeted blockade of the interaction between CD47 and SIRPα can potentially enhance the phagocytic activity of macrophages against tumor cells, thereby promoting the body’s immune response to the tumor." (PMID 41341383, 2025). "Research indicated that anti-GD2/anti-CD47 treatment engages these TAMs in the anti-tumor response, facilitating complete tumor eradication." (PMID 40534850, 2025). "Antibodies blocking CD47 were shown to reduce tumor size and inhibit metastasis by enhancing cancer cell clearance through macrophages." (PMID 41233805, 2025). "The promotion of MHC II + macrophages, representing M1-type macrophages, demonstrated that CD47-gene silencing was able induced proinflammatory effects during tumor cleaning." (PMID 40006507, 2025). "Congruent with the in vitro results, VOR administration significantly boosted the levels of CD47 in the tumor tissues of HCT116-bearing mice." (PMID 39994810, 2025). "Herein, we reported that miR-96-5p was clinically inversely correlated with CD47 and acted as a tumor-suppressive miRNA in PDAC." (PMID 41350707, 2025). "Competitive binding of anti-CD47 antibodies to CD47 on tumor cells blocks the interaction between CD47 and SIRPα on CAR-Ms, thereby reversing macrophage immune suppression and significantly enhancing the phagocytic activity of CAR-Ms." (PMID 40814015, 2025). "The first is by blockading the CD47-SIRPa interaction which normally stimulates macrophage phagocytosis of tumor cells." (PMID 40507328, 2025). "Nevertheless, inhibition of CD47/SIRPα interaction monotherapy is insufficient to control tumor progression in some cancers which will require combination treatment to achieve synergistic effects." (PMID 40070841, 2025). "Research has shown that CD47 can evade tumor immunity, affect tumor progression and metastasis, and participate in processes such as cell apoptosis, proliferation, adhesion, and migration." (PMID 40124370, 2025).
tumor (continued). "PAR2 also plays a role in cancer development, promoting tumour proliferation, angiogenesis and expression of immune checkpoint inhibitors (like PD-L1, CD47 and CD24)." (PMID 40806209, 2025). "Another dual-targeting strategy involves targeting CD47, a molecule that inhibits immune-mediated clearance of both healthy and tumor cells." (PMID 41335396, 2025). "Reciprocally, HDACi-upregulated CD47 polarized macrophages towards a pro-tumor M2 phenotype through SIRPα ligation." (PMID 39994810, 2025). "Subsequently, bsAbs targeting a TAA and blocking the CD47–SIRPα axis to dampen on-target off-tumor toxicities in solid tumors, were developed." (PMID 40402266, 2025). "Elevated CD47 inhibits macrophage phagocytosis of tumor cells, while higher TIPRL levels enhance tumor cell proliferation and survival." (PMID 40740874, 2025). "NDV has yet to be evaluated in combination with an ICI that targets a tumor:innate immune signaling pathway, such as CD47:SIRPα." (PMID 41322194, 2025). "In this study, we established a mouse model of partial or complete tumor resection mediated by CD47‐targeted OMI." (PMID 40385528, 2025). "The increase in tumor cell surface CRT is also positively correlated with the efficacy of anti-CD47 antibody-induced phagocytosis." (PMID 40733687, 2025). "The high co-expression of B7-H3 with HER2 was identified as an independent risk factor for poorer overall survival (OS), and CD47 co-expression was associated with worse outcomes than the expression of either B7-H3 or CD47 alone in tumor samples (p = 0.0007)." (PMID 40214484, 2025). "Knockdown of Cd47 impaired tumor growth in an orthotopic syngeneic mouse model, and less infiltration of Th2 cells into tumors was observed in Cd47‐knockdown RENCA tumors, as determined by flow cytometry." (PMID 40548645, 2025). "Inhibition of CBX3 or lactate production has been found to reduce CD47 expression, restore phagocytic function, and inhibit tumor growth." (PMID 41463052, 2025). "Strikingly, combining IR700@Nb289‐OMVs (single dose) with CD47 nanobodies (two doses) achieved partial tumour eradication and durable immunological memory in subcutaneous and metastatic CRC models, outperforming PD‐1 blockade." (PMID 40240911, 2025). "We administered oAd-CD47 intratumorally, aligning with the established clinical practice of delivering oncolytic adenoviruses directly to the tumor site." (PMID 40814015, 2025). "A pan‐cancer analysis of CD24/CD47 expression from TCGA showed an extensive overexpression across 31 tumor entities compared to normal tissues." (PMID 41354057, 2025). "Together, these results demonstrate that RASON activates CD47 expression in cancer cells and inhibits macrophage-mediated phagocytosis, thereby enabling innate immune evasion and driving aggressive tumor progression." (PMID 40128846, 2025). "CD47 expressed on the surface of tumor cells releases a “don’t eat me” signal to prevent tumor cells from the immune attack." (PMID 40908470, 2025). "Inhibiting the interaction between Kupffer cells and tumor cells through blocking SIPRα-CD47 enhances phagocytosis of Kupffer cells on tumor cells." (PMID 39820040, 2025). "A nonpathogenic ECN strain was also genetically modified to specifically release CD47 nanoantibody antagonists (CD47 nb) in the tumor microenvironment, increasing the viability of tumor‐infiltrating T‐cells and promoting rapid tumor regression." (PMID 40395752, 2025). "Our findings further demonstrate that IL-8 signalling through CXCR2 upregulates CD47 expression in tumour cells, potentially influencing macrophage behaviour within the TME." (PMID 41163221, 2025). "Tumor cells often overexpress CD47 to escape immune system attacks, making CD47 an important target in cancer therapy." (PMID 40072049, 2025).
tumor (continued). "There is evidence that relieving immunosuppression (e.g., blocking CD47 on tumor cells) can activate intra-tumoral DCs and crosstalk with NK cells, suggesting that innate checkpoints on DCs/macrophages are manipulable to improve DC function." (PMID 40227782, 2025). "CD47 is often upregulated in tumor cells, where it interacts with SIRPα on surfaces of macrophages, to release the self-recognition signal, and thereby evading CAR-Ms phagocytic activity." (PMID 40814015, 2025). "Confocal microscopy and live imaging revealed that CD47 blockade increased macrophage-tumor cell contact in terms of both frequency and duration, facilitating more trogocytic events." (PMID 41181711, 2025). "The interaction of CD47 with TSP‐1 (Thrombospondin‐1) contributes to tumour progression by inhibiting angiogenesis." (PMID 41195773, 2025). "Nanoparticles coated with CD47 can interact with SIRPα on macrophages to avoid clearance, while those designed to block CD47–SIRPα interactions can promote the phagocytosis of tumor cells by inhibiting this signaling pathway." (PMID 40801742, 2025). "Core-shell anti-phagocytosis-blocking repolarization-resistant membrane-fusogenic liposome and M1- MΦM (ARMFUL/M1) MΦM presents CD47, which enhances macrophage phagocytosis towards the tumor." (PMID 40225567, 2025). "Tumor cells exploit this pathway to evade recognition and phagocytosis by macrophages by upregulating CD47 expression." (PMID 40429702, 2025). "TUNEL staining showed that DMPLAC promoted necrosis of the tumor tissue, and CD47 knockdown further enhanced this effect." (PMID 40006507, 2025). "Ultimately, these results emphasize context-dependent efficacy of NDV-mediated CD47 blockade and highlight the impact of tumor intrinsic characteristics in determining responsiveness to immunotherapy." (PMID 41322194, 2025). "Immunotherapy involves the use of immune checkpoint inhibitors (ICIs) to specifically block immune checkpoints such as PD-L1, CTLA-4, and CD47, thereby disrupting the immunosuppressive tumor microenvironment." (PMID 40547026, 2025). "CD47, in addition to its role in fusion, acts as a phagocytosis-suppressing signal, helping tumour cells and CTCs evade recognition and phagocytic clearance by the immune system." (PMID 39967663, 2025). "Overexpressed on tumor cells, CD47 binds SIRPα on macrophages, leading to phosphorylation of immunoreceptor tyrosine-based inhibitory motifs (ITIMs) and inhibiting phagocytosis." (PMID 40079009, 2025). "One promising target is CD47, a molecule on tumor cells that sends a “don’t eat me” signal to immune cells and helps cancer escape immune destruction." (PMID 41514569, 2025). "A previous study demonstrated that the combination of CAR-T cell therapy with the CD47–SIRPα axis blocker CV1 can potentiate anti-tumor effects." (PMID 40487639, 2025). "successfully detected m6A modifications on CD47 mRNA from liquid biopsy samples, highlighting a novel approach for monitoring tumor-derived RNA." (PMID 40740874, 2025). "These OMVs not only leveraged their inherent PAMPs to engage TLRs on TAMs, but also targeted CD47-expressing tumor cells." (PMID 41035884, 2025). "This contrasts with the tumor cell clearance functions of CD47 and PD-L1, which inhibit the activity of T cells and phagocytes." (PMID 40909948, 2025). "Investigational agents targeting CD47, such as magrolimab, aim to induce phagocytosis of tumor cells by TAMs." (PMID 41415295, 2025). "In conclusion, the SIRPα mutant engineered by oAd-SA has demonstrated remarkable efficacy, achieving a substantial reduction in CD47 expression across a variety of mouse tumor cell lines." (PMID 40070841, 2025). "It was found that SHP2 deneddylation, through the CD47/SIRPα axis, mediated tumor immune suppression in colon cancer, and the administration of allosteric SHP2 inhibitors sensitized immunotherapy-resistant colorectal cancer to immunotherapy." (PMID 40861801, 2025).
tumor (continued). "So in order to counter with this action, tumor cells start to express more CD47 lignads on their surface." (PMID 40469777, 2025). "Studies have shown that the in vivo blockade of an immune checkpoint (CD47) in conjunction with a chemotherapeutic agent increased survival and reduced tumor burden." (PMID 40356923, 2025). "Block CD47‐SIRPα and activate related signaling pathways in phagocytes to enhance phagocytosis and degradation of tumor cells." (PMID 40657202, 2025). "CD47 is ubiquitously expressed, but many tumor cells overexpress this protein as a protection mechanism." (PMID 40408355, 2025). "For PNETs, blocking the CD47-SIRPα interaction promotes macrophages to engulf tumor cells in addition to priming for T cell activity." (PMID 40565098, 2025). "By targeting PD-L1 for selective delivery and silencing CD47 via siRNA, this chimera enables dual checkpoint blockade and electively accumulates in tumor-infiltrating Treg cells." (PMID 41402667, 2025). "In the DMPLAC/siD47 complex, bacterial lysate–modified DMPLAC acts as an immunostimulant, whereas siCD47 blocks the SIRP-α/CD47 pathway to improve the immunogenicity of tumor cells, making it easier for them to be cleared by immune cells activated by DMPLAC." (PMID 40006507, 2025). "Combining nanobody‐engineered OMV‐mediated photoimmunotherapy with CD47 blockade effectively suppressed primary and metastatic tumours, establishing sustained antitumour immune memory." (PMID 40240911, 2025). "Another immune checkpoint, often referred to as the ‘don’t eat me’ signal, involves CD47, a molecule frequently overexpressed on tumor cells." (PMID 41019052, 2025). "Blockade of the CD47/SIRPα axis enhances macrophage-dependent phagocytosis of tumor cells, establishing this immune checkpoint as a therapeutic target in cancer immunotherapy." (PMID 40578556, 2025). "By pairing CD47 blockade with tumor-specific targets (e.g., CD20 or EpCAM), these agents achieve selective activity on malignant cells while sparing RBCs and other healthy tissues." (PMID 41179296, 2025). "CD47 is an immunoregulatory checkpoint molecule highly expressed on tumor cells and regulated through diverse mechanisms." (PMID 40948940, 2025). "More recent studies also showed that anti-CD47 therapies in mouse tumor models activate adaptive immune responses." (PMID 41350707, 2025). "Anti-CD47 antibodies can block the CD47-SIRPα pathway, restoring the phagocytic function of macrophages and enhancing their ability to recognize and kill tumor cells." (PMID 40821806, 2025). "SIRPα inhibits macrophage phagocytosis by interacting with its ligand, CD47, a key immunosuppressive signaling molecule involved in the immune escape of tumor cells." (PMID 40356928, 2025). "Their infiltration correlates with tumor grade and recurrence, with cluster of differentiation 47 (CD47) signaling aiding immune evasion." (PMID 40948940, 2025). "These antibodies exhibit higher affinity and binding activity for CD38 than for CD47, reducing potential on-target and off-tumor effects." (PMID 40013150, 2025). "Collectively, these findings highlight the therapeutic promise of targeting the CD47-SIRPα axis, particularly when combined with PD-1 blockade, to enhance anti-tumor immunity and overcome resistance mechanisms in cHL." (PMID 40806636, 2025). "DMPLAC nanoparticles and CD47-gene silencing both effectively reduced tumor vessels, as shown by CD31 staining." (PMID 40006507, 2025). "The combination of the Vpr peptide and the CD47 inhibitor SIRPαFc fusion protein can exert a synergistic effect, significantly inhibiting the growth of the distant tumor." (PMID 40733687, 2025). "Engineered exosomes expressing SIRPα, PD-1, and LILRB1 interact with receptors on tumor cells (CD47, PD-L1, and B2M), promoting the phagocytosis of tumor cells and enhancing antigen presentation by immune cells." (PMID 39465690, 2025).